CDK4 (cyclin dependent kinase 4)
Diseases named in the same sentence as CDK4 in open-access papers (continued):
Sharing a sentence is not in itself a finding about the gene and the disease.
sarcoma (continued). "Among the tested 59 sarcoma TMA cases, 52 (88.1%) of the tissues express CDK4." (PMID 29670090, 2018). "Our results showed that CDK4 expression significantly correlated with a higher clinical stage and a higher TNM grade of synovial sarcoma patients, and a worse clinical prognosis of sarcoma patients." (PMID 29670090, 2018). "On further analysis, significant correlations are not found between CDK4 expression and sarcoma patient age, gender, sarcoma type, and tumor location." (PMID 29670090, 2018). "Treating these sarcoma tumors with the CDK4 inhibitor palbociclib revealed that tumors expressing high levels of CDK4 mRNA, but not those expressing low CDK4 and high p16INK4a levels, responded to palbociclib." (PMID 26528855, 2015). "It is well known that WDLPS and DDLPS present amplification of MDM2 and CDK4 genes on chromosome 12q13–15 as opposed to benign adipose tumors and other sarcoma subtypes." (PMID 25888631, 2015). "Palbociclib is also active in vivo against sarcomas displaying high levels of CDK4 but not against sarcomas displaying low levels of CDK4 and high levels of p16ink4a." (PMID 26528855, 2015). "Downregulation of p21Cip1 and higher expression of CDK4-cyclinD1 and CDK2-cyclinE could accelerate cell cycle in sarcomas." (PMID 22852096, 2012). "These genetic alterations closely resemble the genomic profile of other sarcomas that respond to CDK4/6 inhibition, suggesting a potential therapeutic strategy involving CDK4/6 inhibitors, either as a single agent or in combination with MDM2 inhibitors, for BCOR-fusion-positive sarcomas." (PMID 40001568, 2025). "Indeed, it would be valuable to determine the clinical outcome, in terms of PFS and OS, of an advanced and progressing independent sarcoma population exhibiting overexpression of CDK4, without overexpression of CDKN2A." (PMID 37875500, 2023). "Moreover, palbociclib was active in vivo against subcutaneously engrafted CDK4-expressing sarcomas, although responses were negative in tumors displaying low levels of CDK4 and high levels of p16ink4a." (PMID 36839989, 2023). "Further studies explored the relationship between CDK4 expression and clinicopathological characteristics using a TMA containing 50 synovial sarcoma cases with clinical information, and a TMA containing 59 various sarcoma cases with up to 112 months of follow-up data." (PMID 29670090, 2018). "Thus, repression of HRAS following CDK4 inhibition was not specific to sarcoma cell lines." (PMID 28855512, 2017). "Preclinical investigators of this study found that CDK4 overexpression, while not of CDKN2A, was the most consistent predictive factor for palbociclib efficacy in sarcomas." (PMID 37875500, 2023). "Functional diversity of CDK4 and CDK6 have not been investigated in sarcomas and warrants further investigation." (PMID 36612255, 2022). "These reveal CDK4 and XPO1 as potential targets for a paediatric undifferentiated sarcoma that does not have genomic alterations or amplifications in these genes." (PMID 27329820, 2016). "Amplifications of CDK4 and CCND1 (cyclin D1) were observed in 11% and 4% of the sarcomas respectively, but never in tumours with CDKN2 deletions." (PMID 7640224, 1995). "CDK1 inhibitors currently are not available for sarcomas, as well as CDK4/6 targeted inhibitors such as palvociclib and ribociclib which are approved for breast cancer by the US Food and Drug Administration (FDA) also have not been approved yet for sarcomas." (PMID 38434982, 2024). "Furthermore, using total RNA, and not DNA samples, the fusion genes of various sarcomas could be identified, such as HMGA2-LPP and TLS-CHOP, while detecting MDM2 and CDK4 overexpression by quantitative real-time PCR." (PMID 24965044, 2014).
ovarian carcinoma (111 papers, 2007 to 2026). A malignant neoplasm originating from the surface ovarian epithelium. "Deregulated CDK4/6 activity promotes uncontrolled cellular proliferation and is associated with the tumorigenesis of different types of cancer, including ovarian cancer." (PMID 39409889, 2024). "A previous in vitro study showed that ovarian cancer cell lines with p16 loss but with intact pRB were more sensitive to CDK4/6 inhibitors." (PMID 36528667, 2022). "We recently uncovered that SMARCA4 loss in an ovarian cancer subtype causes cyclin D1 deficiency leading to susceptibility to CDK4/6 inhibition." (PMID 30718506, 2019). "As multiple genes in the CDK4/6 pathway are commonly mutated or dysregulated in ovarian cancer, we evaluated the efficacy of the CDK4/6 inhibitor Ribociclib alone, in combination with chemotherapy, and as maintenance therapy in several models of HGSOC." (PMID 29644000, 2018). "Overexpression of CDK4 found to be linked to the development of paclitaxel resistance in ovarian cancer cells." (PMID 29867487, 2018). "Moreover, the suppression of CDK4 enhances the susceptibility of paclitaxel in multidrug-resistant ovarian cancer cells." (PMID 38415456, 2025). "The association between CDK4/6i with anti-hormonal therapies certainly deserves to be mentioned for its promising results in gynecological malignancy, particularly in hormone receptor positive endometrial and ovarian cancers where endocrine agents are generally used alone in later treatment lines." (PMID 34204543, 2021). "Thus, network-based INCM analysis generates a hypothesis for a potential synthetic lethal interaction for CETN2 and CDK4 co-mutated ovarian cancer." (PMID 32101536, 2020). "Sum up, our research reports that Kirenol effectively suppresses the growth and movement of ovarian cancer cells by specifically targeting the PI3K/AKT/CDK4 signaling pathway." (PMID 38415456, 2025). "A few preclinical studies investigated co-treatment with ICIs and CDK4/6 inhibitors in ovarian cancer." (PMID 40856900, 2025). "The ability of the PI3K/AKT/CDK4 signaling pathway to hinder the growth, movement, and programmed cell death of ovarian cancer cells establishes a solid basis for further investigation and potential use in the management of ovarian cancer." (PMID 38415456, 2025). "Overall, this study proved that the combined treatment strategy of CDK4/6 and PD-1 inhibitors holds great promise and offers potential for treating poorly immune-infiltrated ovarian cancers." (PMID 40856900, 2025). "Since CDK6 is a potential resistance marker of MEKi, as well as a single therapeutic target for ovarian cancer patients, we selected palbociclib as the specific inhibitor of CDK4/6 to use in combination with MEKi." (PMID 40568132, 2025). "The possibility that Kirenol affects the function of ovarian cancer cells by changing the PI3K/AKT/CDK4 signaling pathway is indicated by all these findings." (PMID 38415456, 2025). "Genistein has indicated upregulation of cyclin D1 and CDK4 expression, thereby promoting the proliferation and viability of ovarian cancer OVCAR‐5 cells." (PMID 40634118, 2025). "The novel compound ZC-22, a PARP and cyclin-dependent kinase 4/6 dual inhibitor, shows high therapeutic potential to significantly improve the response of ovarian cancer to cisplatin." (PMID 39224110, 2024). "Palbociclib showed longer progression-free survival and excellent tolerance, revealing the potential therapeutic effects of cyclin-dependent kinase 4/6 inhibitors in recurrent ovarian cancer." (PMID 39224110, 2024). "Early investigation with the CDK4/6 inhibitor palbociclib showed single-agent activity with limited efficacy in heavily pretreated unselected ovarian cancers (NCT01536743)." (PMID 39409889, 2024). "A combination of a CDK4/6 inhibitor palbociclib with olaparib in ovarian cancer cell models demonstrated a synergistic effect in MYC-overexpressing cells, presumably via palbociclib-induced HRD." (PMID 39594684, 2024).
ovarian carcinoma (continued). "The authors use single-cell RNA-sequencing and TCR tracking to analyze blood and tumors from breast and ovarian cancer patients treated with PD-1 blockade and CDK4/6 inhibition." (PMID 36688919, 2023). "We performed single-cell RNA-sequencing and T cell receptor clonotype tracking of breast and ovarian cancer patients treated with the CDK4/6 inhibitor ribociclib and PD-1 blockade." (PMID 36688919, 2023). "In ovarian cancer cells, miR-506 has been shown to induce senescence by directly targeting the CDK4/6-FOXM1 axis." (PMID 35884996, 2022). "Apart from preclinical studies, several clinical trials revealed that MEK inhibitor trametinib, Wee1 inhibitor adavosertib, and CDK4/6 inhibitor ribociclib showed preliminary efficacy in ovarian cancer." (PMID 36275669, 2022). "All together, these studies support our findings that combination of CDK4/6 and PARP inhibition by ZC-22 displays anti-tumor efficacy in breast and ovarian cancers beyond HR deficiency." (PMID 35270034, 2022). "Unexpectedly, we found that ZC-22 showed a stronger anti-tumor effect than the combination of CDK4/6i Abemaciclib and PARPi Olaparib in breast and ovarian cancer at the same concentration." (PMID 35270034, 2022). "Recently, CDK4/6i have shown potent antitumor activity in ovarian cancer either as single agent or in combination with platinum-based chemotherapy in several clinical trials." (PMID 35270034, 2022). "In recent years, three PARP inhibitors and three CDK4/6 inhibitors have been approved by the FDA for the treatment of recurrent ovarian cancer and advanced ER-positive breast cancer, respectively." (PMID 35270034, 2022). "Downregulation of EPAC1 in ovarian cancer cells greatly reduces phosphorylated protein kinase B (pAkt), cyclin D1, and cyclin-dependent kinase 4 (CDK4) signaling." (PMID 35805104, 2022). "Hyper-activation of CDK4/6 exists in most of the breast and ovarian cancer cells, resulting in uncontrolled cell proliferation." (PMID 35270034, 2022). "Recently, therapeutic synergy between PARPi and CDK4/6i has been demonstrated in breast and ovarian cancer patients with HR proficiency." (PMID 35270034, 2022). "This article reviews the rationales of combining paclitaxel with CDK4/6i as a potential therapeutic option in recurrent ovarian cancer." (PMID 36185294, 2022). "Here, we describe the possible biological role of CDK4 and CDK6 complexes in ovarian cancer and provide the rationale for the use of CDK4/6 inhibitors in this pathology, alone or in combination with other drugs." (PMID 34204543, 2021). "The effectiveness of the CDK4/6 inhibitors as single agent (palbociclib) was explored in a phase II trial in heavily pretreated ovarian cancer patients." (PMID 34204543, 2021). "In general, it was observed that CDK6, more than CDK4, was expressed at high levels in epithelial ovarian cancer." (PMID 34204543, 2021). "On the basis of these promising preclinical results, the use of CDK4/6i to increase the platinum efficacy in ovarian cancer patients is currently being tested in several clinical trials." (PMID 34204543, 2021). "Our results showed that BTG2 expression regulated ovarian cancer cell proliferation via G1/S phase cell cycle arrest by regulating Cyclin D1, CDK4, p-AKT, and p-ERK expression." (PMID 34485119, 2021). "More than one hundred clinical trials for CDK4/6 inhibitors in breast, but also in other cancers, including glioma, sarcoma, lung, pancreatic, head and neck, colorectal, prostate and ovarian cancer, are actively recruiting patients or about to initiate." (PMID 32385714, 2020). "Especially, deregulation of the CDK4/6–cyclin-D/p16–Rb signaling pathway is commonly found in ovarian cancer." (PMID 32862831, 2020).
ovarian carcinoma (continued). "We show that the combination of CDK4/6i and PD-1 blockade has synergistic activity in the treatment of ovarian cancer." (PMID 32929370, 2020). "Emerging evidence also shows that CDK4/6is suppress ovarian cancer progression both in vitro and in vivo." (PMID 32929370, 2020). "In accordance with this, our study also find that CDK4/6 inhibition can suppress tumor progression in syngeneic mouse ovarian cancer model." (PMID 32929370, 2020). "We therefore tested CDK4/6 inhibition with Ribociclib both in vitro and in vivo and demonstrated a significant delay in ovarian cancer cell growth via the induction of a pseudo-senescent state." (PMID 29644000, 2018). "Given that multiple previous reports have shown dysregulated cell cycle gene expression within the known CDKN2A/Cyclin D1-CDK4-CDK6/Rb axis, CDK4/6 inhibition represents a promising approach in ovarian cancer." (PMID 29644000, 2018). "Our previously published results concerning the action of leptin receptor antagonists on epithelial ovarian cancer cells showed that both antagonists studied decreased cdk2 and cdk4 protein expression in CaOV-3 and OVCAR-3 cells." (PMID 28861689, 2017). "In epithelial ovarian cancer, Rb proficient cell lines with low p16 expression were most responsive to CDK4/6 inhibition." (PMID 28472136, 2017). "Overexpression of miR-506 inhibited proliferation and promoted senescence of ovarian cancer cells via direct targeting CDK4 and CDK6." (PMID 27542202, 2016). "In ovarian cancer, miR-506 can suppress proliferation and induce senescence by directly targeting the CDK4/6-FOXM1 axis." (PMID 26452129, 2015). "Using ovarian cancer as a model system, we have compared directly the acute effect of selective CDK4/6 inhibition (PD0332991 = palbociclib) or CDK2 inhibition (SNS032, dinaciclib), as well as mechanisms of resistance." (PMID 25557169, 2015). "There has been a recent interest in exploring the combination of letrozole and CDK4/6 inhibitors in recurrent ER+ ovarian cancers." (PMID 26043844, 2015). "The cyclin D1/CDK4 complex is responsible for cell cycle progression in early G1 phase and is frequently overexpressed in various human carcinomas including ovarian cancer." (PMID 25180593, 2014). "In the GBM data, the involved pathways include parts of the RB signaling and RTK signaling pathways (CDKN2B, CDK4; EGFR, NF1 ), and in the ovarian carcinoma data a recurrent mutated module related to cell cycle and DNA repair (CCNE1, MYC, RAD52 ) is revealed." (PMID 24565034, 2013). "Abemaciclib, a selective CDK4/6 inhibitor, has significantly improved outcomes in hormone receptor-positive breast cancer and is being actively explored in tumors characterized by cell cycle dysregulation, including endometrial and ovarian cancers." (PMID 42194689, 2026). "Additionally, CDK4 plays vital functions in facilitating the growth and spread of ovarian cancer cells." (PMID 38415456, 2025). "In summary, the combined results of our network pharmacology analysis and in vitro tests emphasized that Kirenol hinders the growth of ovarian cancer cells, causes cell cycle arrest, enhances apoptosis, and hampers migration, possibly by regulating the PI3K/AKT/CDK4 signaling pathway." (PMID 38415456, 2025). "In the murine ovarian cancer model, the CDK4/6i abemaciclib alone could enhance immune cell infiltration in tumors, particularly CD8+ T-cell and B-cell infiltration." (PMID 39593745, 2024). "Similarly, reduction of levels of the ribosomal protein RPS6 in ovarian cancer cells caused downregulation of CDK2, CDK4, CDK6, cyclin E, and cyclin D1, thereby blocking the transition from G0/G1 to S phase and suppressing cell proliferation." (PMID 38802745, 2024).
ovarian carcinoma (continued). "Interestingly, cytoplasmic expression of CDK4, cyclin D1 and cyclin E1 also has predictive and/or prognostic significance in ovarian cancers." (PMID 38612869, 2024). "This study assesses a potentially novel combination of CDK4/6 inhibition with chemotherapy in ovarian cancer and demonstrates the safety and promising efficacy of sequencing this class of drugs with standard-of-care chemotherapy in ovarian cancer." (PMID 35972817, 2022). "Combining cyclin-dependent kinases 4 and 6 (CDK4/6) inhibitor abemaciclib and anti-PD-1 therapy may have a better promise for poorly immune-infiltrated ovarian cancer." (PMID 36275669, 2022). "There are several ongoing and completed Phase II/III studies testing dual CDK4/6 inhibitors against breast and ovarian carcinomas, further verifying the antitumor effectiveness of this group of drugs, some of which already manifesting superiority over ET in monotherapy." (PMID 35681689, 2022). "Current studies have shown therapeutic synergy for combinations of PARPi and CDK4/6i in breast and ovarian cancers with homologous recombination (HR) proficiency, which represents a new synthetic lethal strategy for treatment of these cancers regardless HR status." (PMID 35270034, 2022). "However, the clinical benefits of CDK4/6i are limited and were only observed in a fraction of breast and ovarian cancer patients." (PMID 35270034, 2022). "The combination of CDK4/6 inhibitors with other agents might be a more effective strategy to improve clinical outcomes and to extend the use of CDK4/6 inhibitors to a broader spectrum of breast and ovarian cancer patients than CDK4/6i alone." (PMID 35270034, 2022). "With the realization of the non-mitotic mechanism of paclitaxel in killing cancer cells, a new rationale may motivate the study of adding CDK4/6i to paclitaxel regimen, especially to the dose dense treatment of metastatic breast and recurrent ovarian cancer." (PMID 36185294, 2022). "Interestingly, preclinical studies of the CDK4/6 inhibitor ribociclib in ovarian cancer demonstrated synergistic effects when combined with cisplatin, increasing ovarian cancer cell death." (PMID 35972817, 2022). "Thus, the possibility of a paclitaxel and CDK4/6i combination as a chemotherapy regimen for ovarian cancer exists." (PMID 36185294, 2022). "To investigate whether ZC-22 retained the CDK4/6 inhibitory activity of Abemaciclib, we determined the Rb phosphorylation and cell-cycle distribution in breast and ovarian cancer cells treated with Abemaciclib (LY-2) or ZC-22." (PMID 35270034, 2022). "However, little information of CDK4/6i in ovarian cancer treatment has been reported yet, though substantial interests prompt ongoing efforts to evaluate a potential role in ovarian cancer treatment." (PMID 36185294, 2022). "However, the data from GSE17260 suggested that the expression of CDK4 was higher, the prognosis of ovarian cancer patients was poorer." (PMID 35095879, 2021). "However, possible applications of CDK4/6 inhibitors in patients with ovarian cancer is still under evaluation." (PMID 34204543, 2021). "Slamon and colleagues firstly tried to identify which ovarian cancer type may be sensitive to the CDK4/6i." (PMID 34204543, 2021). "Since PARPi increases genomic instability in cancer cells and CDK4/6i impair the DDR, this strategy could induce HR deficiency, even in HR proficient ovarian cancers." (PMID 34204543, 2021). "We also found that the mimics of hsa-mir-330-5p upregulated CDK4/6 in ovarian cancer cell lines." (PMID 35095879, 2021). "Another example of a gene commonly inactivated by structural variants is RB1, an important biomarker of resistance to CDK4/6 inhibitors such as palbociclib, with this class of event contributing to 47% and 43% of RB1 inactivation in breast and ovarian cancer respectively." (PMID 33144218, 2020). "In ovarian cancer patients, CDK4/6is have achieved stable disease or a durable CA-125 response." (PMID 32929370, 2020).